LRP6 (LDL receptor related protein 6)
Diseases named in the same sentence as LRP6 in open-access papers (continued):
Sharing a sentence is not in itself a finding about the gene and the disease.
atherosclerosis (continued). "And we found that mutant LRP6 stimulate endothelial cells proliferation and migration to minor extent compared with wild type, suggesting individuals with these mutation could suffer from atherosclerosis more easily as their ability to repair denuded vessel wall reduced." (PMID 24427284, 2014). "LRP6 is a Wnt co-receptor and is linked to metabolic diseases in humans since several loss-of-function mutations within LRP6 were shown to cause hypertriglyceridemia, hypercholesterinemia, NAFLD and atherosclerosis." (PMID 39037913, 2024). "LRP6 provides key protection against dyslipidemia and atherosclerosis." (PMID 38139440, 2023). "Furthermore, the mutant LRP6 triggers atherosclerosis by activating platelet-derived growth factor (PDGF)-dependent vascular smooth muscle cell differentiation." (PMID 26046396, 2015). "Impaired function of LRP6 presents with elevated serum LDL and TG and fasting glucose levels, which together constitute the major components of metabolic syndrome and are major risk factors for atherosclerosis and diabetes." (PMID 26046396, 2015). "Furthermore, low plasma levels of Wnt1 and high plasma levels of the LRP6 antagonists sclerostin and DKK1 have been associated with the risks for hyperlipidemia and atherosclerosis." (PMID 26046396, 2015). "Because the initial discovery that LRP6 plays a pivotal role in metabolic syndrome and atherosclerosis, it has become a major focus of scientific investigations on hyperlipidemia, non-alcoholic fatty liver disease, and coronary artery disease (CAD), as well as their associated risk factors." (PMID 26046396, 2015). "Patients carrying an LRP6 mutation exhibit elevated levels of LDL cholesterol, triglycerides, and fasting glucose, which cooperatively constitute the risk factors of metabolic syndrome and atherosclerosis." (PMID 26046396, 2015). "We pursued further experiments assessing whether LRP6 could affect endothelial cells function in the pathogenesis of atherosclerosis." (PMID 24427284, 2014). "Reduced LRP6 expression levels in carotid atherosclerotic lesions led to retarded Wnt signaling which may contribute to atherosclerosis development." (PMID 24427284, 2014). "In summary, as a potential target, the elevated expression level of LRP6 protein is strongly correlated with malignancy and the poor prognosis of tumors, and targeting LRP6 may provide a new approach for the treatment of complex diseases, such as cancer, atherosclerosis, and Alzheimer’s disease." (PMID 37175248, 2023). "Furthermore, patients carrying an LRP6 mutation exhibit elevated levels of LDL-c, TC, and fasting glucose, which constitute the risk factors of the diseases including hypertriglyceridemia, hypercholesterolemia, atherosclerosis and NAFLD." (PMID 26735337, 2016). "Also this mutation in LRP6 could increase PDGF-dependent vascular smooth muscle cell proliferation, which contributes to development of early atherosclerosis in humans." (PMID 24427284, 2014). "Taken together, the downstream genes of ARL4C, including ABCA1, ALDH1A3, ARF6, ENHO, FLNA, LRP6, OSBPL5, Snail2, and SOX2 play an important role in atherosclerosis." (PMID 40176913, 2025). "LRP6 suppressed VSMC differentiation and atherosclerosis by suppressing platelet-derived growth factor (PDGF) expression." (PMID 40176913, 2025). "Interestingly, ARL4C promoted the expression of LRP6, WNT5A, and WNT11, which suggests that ARL4C suppresses atherosclerosis development by enhancing LRP6 expression." (PMID 40176913, 2025). "Related to vascular calcification, PRMT4-mediated Opn gene expression is elevated as a consequence of the SMC-specific reduction of the WNT signaling receptor, low-density lipoprotein receptor-related protein 6 gene (LRP6), ultimately promoting atherosclerosis." (PMID 39453431, 2024). "In addition, when the LRP6 mutant impaired Wnt-LRP6 signaling, hyperlipidemia, non-alcoholic fatty liver disease, and atherosclerosis developed." (PMID 26046396, 2015).
tooth agenesis (23 papers, 2016 to 2026). A tooth disease characterized by failure to develop one or more missing teeth. "The molecular and functional analyses of LRP6 variants associated with nonsyndromic tooth agenesis reveal diverse pathogenic mechanisms that converge on the disruption of Wnt/β-catenin signalling." (PMID 41505923, 2026). "While this investigation offers significant insights into LRP6-associated tooth agenesis, it is imperative to acknowledge several inherent limitations." (PMID 41505923, 2026). "While Thai probands expanded the phenotype and genotype spectrum of LRP6-associated tooth agenesis, a review of 20 studies showed clustering of variants in β-propeller domains (62%), usually autosomal dominant (78%) but with variable penetrance." (PMID 41505923, 2026). "LRP6 variants cause nonsyndromic tooth agenesis in Thai patients by destabilizing the β-propeller and disrupting Wnt signalling." (PMID 41505923, 2026). "Our findings provide genetic and functional evidence linking LRP6 variants to non-syndromic tooth agenesis and expand the variant spectrum for congenital tooth agenesis." (PMID 40534843, 2025). "Variants in LRP6 have been associated with syndromic tooth agenesis, often accompanied by cleft lip and/or palate and minor congenital abnormalities of the fingers and ears." (PMID 40534843, 2025). "And the downstream TG of chr12:12472818-12473034 was LRP6, which was associated with “tooth agenesis”62." (PMID 33824393, 2021). "In conclusion, we identified a novel LRP6 variant, c.1924dup, in a Japanese family with tooth agenesis." (PMID 34285199, 2021). "To date, only 19 LRP6 mutations have been identified in tooth agenesis in six previous studies 1,17–22." (PMID 34759310, 2021). "The results of our study enlarged the LRP6 mutation spectrum of tooth agenesis and demonstrated the LRP6-related tooth agenesis pattern." (PMID 34759310, 2021). "The low-density lipoprotein receptor-related protein 6 (LRP6) gene is a recently defined gene that is associated with the autosomal-dominant inherited tooth agenesis (TA)." (PMID 34306029, 2021). "In summary, the present study investigated a large family with TA and identified a novel diagnostic variant in the LRP6 gene, thereby expanding the mutation spectrum of human tooth agenesis." (PMID 34306029, 2021). "Research has identified an association between mutations in MSX1, PAX9, EDA, AXIN2, WNT10A, WNT10B and LRP6 and human tooth agenesis." (PMID 31914153, 2020). "Previous reported families with tooth agenesis caused by a LRP6 mutation appeared to be nonsyndromic." (PMID 30950205, 2019). "By contrast, frameshift, nonsense and missense mutations in the WNT co-receptor gene LRP6 have been associated with orofacial clefts and tooth agenesis, suggesting that deficient LRP6-mediated canonical WNT signaling has a crucial role in CLP pathogenesis." (PMID 30760477, 2019). "Mutations and genetic variants of this pathway, such as WNT10A, AXIN2 and LRP6, have all been well recognized as susceptibility factors of tooth agenesis." (PMID 27362534, 2016). "Our findings not only corroborate but also significantly expand upon previous reports of LRP6-associated tooth agenesis, reaffirming the gene’s multifaceted contribution to both nonsyndromic and syndromic forms of oligodontia, often mediated by diverse pathogenic mechanisms." (PMID 41505923, 2026). "However, existing data on LRP6-associated tooth agenesis is predominantly derived from European and East Asian cohorts, resulting in a paucity of data regarding other ancestral backgrounds, particularly Southeast Asian populations." (PMID 41505923, 2026). "Yet the pathogenic mechanism of LRP6-related tooth agenesis and the genetic cause for its clinical heterogeneity remain unclear." (PMID 40687612, 2025).
tooth agenesis (continued). "To further explore the role of YWTD targeting in LRP6-associated tooth agenesis, we collected 31 reported LRP6 tooth-agenesis mutations and examined their potential YWTD association using LRP6 crystal structures as reference (LRP6-PE1PE2, 3S94; LRP6-PE3PE4, 4A0P)." (PMID 40687612, 2025). "Notably, most of the tooth agenesis-related LRP6 missense mutations were distributed within the β-propeller modules, whereas the four subsequent EGF-like domains (E1–E4) remained untargeted." (PMID 40687612, 2025). "The severe clinical phenotype of the proband could be explained by synergistic overlapping effects of having two mutations together, similar to recently reported cases of familial tooth agenesis with LRP6 and PAX9 mutations." (PMID 39685785, 2024). "Besides that, due to the loss of information about specific tooth agenesis pattern in patients with LRP6 mutations, the phenotypic variability of LRP6-associated tooth agenesis needs to be further explored." (PMID 34759310, 2021). "WES and Sanger sequencing revealed an unreported heterozygous missense mutation in exon 13 of the LRP6 (c.2840 T > C;p.Met947Thr) in three family members with tooth agenesis (IV:1, III:4, and IV:2) and two family members with tooth agenesis accompanied by hand polydactyly (III:3 and II:3)." (PMID 34759310, 2021). "In addition, several LRP6 variants have been documented in patients with congenital tooth agenesis." (PMID 35052459, 2022). "The data collectively emphasize LRP6 as a significant gene in both isolated and syndromic tooth agenesis, with implications for genetic counselling and molecular diagnostics." (PMID 41505923, 2026). "Recently, a novel single-nucleotide insertion in the LRP6 gene (c.1924dup) was identified via whole-exome sequence analysis in Japanese patients with tooth agenesis (oligodontia)." (PMID 35052459, 2022). "The robust evidence herein unequivocally supports prioritizing LRP6 genetic screening in patients exhibiting severe tooth agenesis, particularly when such presentations are compounded by additional dental anomalies (eg, taurodontism) or suggestive ectodermal signs." (PMID 41505923, 2026). "Both probands presented with tooth agenesis, manifesting as the absence of 20 and 4 permanent teeth, respectively – a pattern highly consistent with previously documented LRP6 pathogenic variants." (PMID 41505923, 2026). "In particular, LRP6 has been discovered as a frequent pathogenic gene for tooth agenesis (absence of one or more permanent teeth) or in rare cases for ectodermal dysplasia where affected members showed variable abnormalities of teeth, hair, and sweat glands." (PMID 40687612, 2025). "We further characterized the phenotype of LRP6-related non-syndromic hypodontia, confirming that the maxillary lateral incisor, mandibular second premolar, and maxillary second premolar were the most commonly missing teeth, consistent with LRP6-related NSO trends." (PMID 40534843, 2025). "Our study report that LRP6 mutation might be associated with hand preaxial polydactyly in humans, which broaden the phenotypic spectrum of LRP6-related disorders, and provide valuable information on the characteristics of LRP6-related tooth agenesis." (PMID 34759310, 2021). "Low-density lipoprotein receptor-related protein 6 (LRP6, OMIM*603507, cytogenetic location: 12p13.2) is a recently discovered pathogenic gene related to tooth agenesis, which was designated as autosomal dominant tooth agenesis, selective 7 (STHAG7; OMIM#616724) in 20151." (PMID 34759310, 2021). "Patients carrying FTA-causing LRP6 mutations primarily exhibit isolated tooth agenesis, although involvement of non-dental tissues has been reported in some cases, such as hair problems and facial clefts." (PMID 34834569, 2021).
tooth agenesis (continued). "Here, we demonstrate an unreported autosomal dominant LRP6 heterozygous mutation (c.2840 T > C;p.Met947Thr) in a tooth agenesis family with hand polydactyly, and another unreported autosomal dominant LRP6 heterozygous mutation (c.1154 G > C;p.Arg385Pro) in a non-syndromic tooth agenesis family." (PMID 34759310, 2021). "However, the roles of plenty of other odontogenic genes which have been reported to be associated with tooth agenesis such as SATB2, BMP4, GREMLIN2, LRP6 and the mechanism of decreased function of hDPSCs in patients with tooth agenesis is still not fully understood." (PMID 34863303, 2021). "Among these 84 patients, 52 patients (62%) presented with LRP6-related NSO, 19 patients (23%) with non-syndromic hypodontia, and 13 patients (15%) with syndromic tooth agenesis." (PMID 40534843, 2025). "Mutations in only seven genes (i.e. AXIN2 [MIM: 604,025], EDA [MIM: 300,451], MSX1 [MIM: 142,983], PAX9 [MIM: 167,416], WNT10A [MIM: 606,268], WNT10B [MIM: 601,906], and LRP6 [MIM: 603,507]) are responsible for the majority of cases with non‐syndromic tooth agenesis." (PMID 30950205, 2019).
coronary artery disease (20 papers, 2011 to 2026). "The relationship between Wnt signaling and coronary artery disease (CAD) was first made evident through the discovery of a mutation in the LRP6 coreceptor, in which hypertensive patients with this mutation were more likely to develop CAD." (PMID 38586172, 2024). "Missense mutations in Wnt co-receptor LRP6 lead to early coronary artery disease in human mutation carriers and knockin mice, who develop hepatosteatosis, even on regular chow diets." (PMID 37684045, 2023). "As WNT signaling is involved in many processes of organogenesis and tissue homeostasis, mutations in LRP6 have been linked to various diseases including coronary artery disease (CAD), high bone mass (HBM) phenotypes, and neural tube defects (NTDs)." (PMID 34834569, 2021). "Any mutation in LRP 6 gene increases risk of coronary artery disease, hypertension, diabetes mellitus type 2, also increases levels of LDL, cholesterol, DKK 1, and also there is abnormal upregulation of inflammation." (PMID 33132762, 2020). "Besides the high bone mass phenotype, heterozygous loss-of-function mutations in LRP6 are previously shown to cause coronary artery disease and tooth agenesis." (PMID 32328030, 2020). "Moreover, accumulating evidences have recently linked LRP6 genetically to early coronary artery disease and abnormal lipids including hypercholesterolemia." (PMID 24906453, 2014). "Additionally, LRP6 is genetically linked to early coronary artery disease and hyperlipemia." (PMID 35187114, 2021). "Literature data show also that a missense mutation in LRP6, which encodes a coreceptor in the WNT signaling pathway, impairs WNT signaling resulting in coronary artery diseases and multiple cardiovascular risk factors." (PMID 41266111, 2026). "We aimed to evaluate the levels of these miRNAs, WNT-proteins (WNT1, -3a, -4, -5a), and LRP6 in adults with coronary artery disease against a control population." (PMID 38139440, 2023). "Previous studies have demonstrated the effects of LRP6 in early coronary artery disease and abnormal blood lipids including hypercholesterolemia, indicating the important role of LRP6 in the MI development." (PMID 24906453, 2014). "LRP6 and LRP4 were previously associated with AD and coronary artery disease." (PMID 33946285, 2021). "However, the relationship between miR-126 and LRP6 associated with coronary artery diseases and HR-exposed HUVECs are not fully explored." (PMID 35082967, 2022). "Downregulated plasma miR-126 levels may be able to serve as a new biomarker for early diagnosis of stable and unstable CAD patients, and mimic-miR-126 could be a potential therapeutic target in atherosclerotic coronary artery disease by inhibiting LRP6 protein expression." (PMID 35082967, 2022). "Mutations in the genes low-density lipoprotein (LDL) receptor-related protein-6 (LRP6) and myocyte enhancer factor 2A (MEF2A) were reported in families with coronary artery disease (CAD)." (PMID 27455246, 2016).
prostate carcinoma (19 papers, 2008 to 2025). A carcinoma that arises from epithelial cells of the prostate gland. "Our study identified mutations in LRRK2 and LRP6 in 7.5% and 2.8% of all prostate cancer patients, respectively, with the majority observed in cases of metastatic prostate cancer." (PMID 40660132, 2025). "The LRP6 gene is known to activate the Wnt/β-catenin signaling pathway, which plays a crucial role in cancer progression, demonstrating significant associations with metastatic and recurrent prostate cancer." (PMID 40660132, 2025). "Our findings suggest that specific genetic mutations, including PIK3CA, LRP6, LRRK2, and BRCA2, are linked to prostate cancer metastasis and BCR." (PMID 40660132, 2025). "LRP5 and LRP6 amplification is observed in up to 7.2% and 2.7% of metastatic prostate cancers, yet are relatively infrequent in primary prostate cancer (0–2.1%)." (PMID 35204808, 2022). "Cav-1 overexpression and inhibition have previously shown to mediate c-Myc level in prostate cancer cell lines through the interaction between Cav-1 and low-density lipoprotein receptor-related protein 6 (LRP6)." (PMID 24939878, 2014). "Treatment of prostate cancer cells with Wnt3A CM or purified recombinant Wnt3A protein significantly enhanced cell growth and migration, while treatment of prostate cancer cells with the LRP6 antagonist Dkk1 significantly inhibited cell growth and migration." (PMID 23469146, 2013). "It was shown that Cav-1 interacts with LRP6 resulting in stimulation of Akt/mTORC1 signaling in prostate cancer." (PMID 24223799, 2013). "Niclosamide was able to suppress LRP6 expression and phosphorylation in all four cancer cell lines, indicating that niclosamide can repress Wnt/β-catenin signaling in breast and prostate cancer cells by suppressing LRP6 expression." (PMID 22195040, 2011). "In support, LRP5 knockdown in PC-3 cells reduced tumor burden and skeletal metastasis in xenografts, and small molecule inhibitors that reduce LRP6 expression and phosphorylation (e.g., niclosamide, salinomycin, and silibinin) can inhibit prostate cancer cell growth and increase apoptosis." (PMID 35204808, 2022). "In the present report, we established a proximity ligation assay (PLA) to detect and quantify the co-localization of FZD6 with the major canonical co-receptor LRP6 as an early event of the well-documented Wnt/β-catenin signal transduction after Wnt10B stimulation in PC-3 prostate cancer cells." (PMID 34769487, 2021). "Interestingly, treatment with recombinant MESD protein, a LRP5/6 chaperone protein able to bind to mature LRP5 and LRP6 on the cell surface, decreases LRP6 phosphorylation in prostate cancer cells, inhibiting their proliferation and tumorigenic potential." (PMID 31412666, 2019). "For instance, androgen-dependent LRP6 expression is necessary for prostate cancer cell growth." (PMID 31412666, 2019). "LRP6 is expressed in human cancer cell lines and up-regulated in human malignant tissues, and LRP6 silencing weakens Wnt/β-catenin signaling and inhibits cell proliferation and tumor growth in breast and prostate cancers." (PMID 28423559, 2017). "Moreover, small molecule inhibitors targeting LRP6 were able to inhibit human breast and prostate cancer cell proliferation." (PMID 23469146, 2013). "Together, these findings suggest that LRP6 is a potential therapeutic target for prostate cancer." (PMID 22195040, 2011). "In the present study, we found niclosamide inhibited the proliferation of prostate cancer PC-3 and DU145 cells with IC50 values less than 1 μM, which are comparable to those shown to suppress LRP6 expression and the activities of Wnt/β-catenin signaling in prostate cancer cells." (PMID 22195040, 2011). "Previous studies showed that LRP6 was important for efficient intoxication of human M2182 prostate carcinoma cells but other studies performed with cells from gene-knockout mice demonstrated no role for either LRP6 or the related LRP5 protein in anthrax toxin entry." (PMID 18350154, 2008).